IL10 (interleukin 10)
Diseases named in the same sentence as IL10 in open-access papers (continued):
Sharing a sentence is not in itself a finding about the gene and the disease.
ankylosing spondylitis (13 papers, 2013 to 2025). An autoimmune chronic inflammatory disorder characterized by inflammation in the vertebral joints of the spine and sacroiliac joints. "Allele and genotype frequency distribution for IL10 −1082 A>G and the association with the risk for ankylosing spondylitis, regardless of HLA-B*27 marker and age in different genetic models." (PMID 34290697, 2021). "In patients with ankylosing spondylitis, curcumin significantly increases the number of Tregs, enhances the expression of transforming growth factor-β (TGF-β) and interleukin-10 (IL-10), and suppresses interleukin-6 (IL-6) levels." (PMID 41458964, 2025). "In an ankylosing spondylitis mouse model, IAA reduced inflammation by suppressing TNF-α, IL-6, IL-17A, and IL-23, while enhancing the expression of IL-10." (PMID 39759289, 2024). "A previous study reported elevated IL-10 concentrations in cancer patients when core temperatures reached 41.8 °C in induced hyperthermia, whilst no IL-10 changes were observed in ankylosing spondylitis patients and healthy control subjects when body core temperatures reached 38.7–39.0 °C." (PMID 39953332, 2025).
autoimmune encephalitis (13 papers, 2012 to 2025). Inflammation of the brain secondary to an immune response triggered by the body itself. "IL-10 deficient mice show a stronger phenotype in several animal inflammatory models, such as chronic enterocolitis, endotoxin shock, and autoimmune encephalitis." (PMID 38480573, 2024). "Reduced expression of C/EBPδ in mice is associated with increased expression of IL10 by dendritic cells with subsequent enhancement of regulatory T-cells and less severe clinical disease when experimental autoimmune encephalitis is induced by vaccination with myelin oligodendrocyte glycoprotein." (PMID 25393235, 2014). "In subsequent studies, the authors identified specific peptide sequences of mycobacterial HSP that stimulated a protective self-HSP cross-reactivity, inducing IL-10 mediated suppression of autoimmune colitis and autoimmune encephalitis." (PMID 36830641, 2023). "When NSC overexpressed IL-10, which transplanted into autoimmune encephalitis mice, they not only inhibited the inflammatory response but also promoted the differentiation of neuronal stem cells into oligodendrocytes and neurons." (PMID 33532127, 2021). "IL-10-producing CD1dhiCD5+ regulatory B cell subset showed a suppressive effect against autoimmune encephalitis." (PMID 27350539, 2016). "PD-L1+, IL-10 expressing macrophages are responsible for initiating antigen tolerance in an autoimmune encephalitis model." (PMID 22844448, 2012). "Also, there was a significant difference between infectious and autoimmune encephalitis regarding CSF levels of IL-10 and CXCL9." (PMID 36048783, 2022). "Moreover, it was observed that IL-10 had higher levels in autoimmune encephalitis compared to autoimmune encephalitis." (PMID 36048783, 2022). "In an experimental autoimmune encephalitis (EAE) model, C-PC decreased disease severity and upregulated key markers of regulatory T cells—FOXP3, CD25, IL-10, and TGF-β—while simultaneously exerting neuroprotective effects that mitigated myelin and axonal damage." (PMID 41514979, 2025). "AE at the time of diagnosis when Plasma IL-1β and IL-10 ratio of mean values in leucine-rich glioma inactivated 1 autoimmune encephalitis (LGI1 AE) vs. non-inflammatory controls." (PMID 40470500, 2025).
chronic GVHD (13 papers, 2009 to 2025). "Protective effects of IL-10+B cells are reported in other diseases such as allogeneic stem cell transplant recipients with chronic graft-versus-host disease." (PMID 40449958, 2025). "As ECP was reported to induce spontaneous release of IL-10 by myeloid CD1c+ DCs isolated from the photophoresate of refractory chronic GvHD patients, we were interested in how in vitro ECP would affect the secretion of cyto- and chemokines by sorted DCs." (PMID 40881697, 2025). "We detected expanded CD163+ host and donor MΦs with low IFN-γ production and a tissue-remodelling cytokine signature (TGF-β, IL-10) in cutaneous aGvHD, and proinflammatory MΦs with decreased IL-10 production in cutaneous chronic GvHD." (PMID 38010706, 2024). "Murine studies have demonstrated that germinal center (GC) B cells are required for the development of chronic GVHD whereas donor-derived IL-10–producing Bregs play a suppressive role in the development of chronic GVHD." (PMID 37092551, 2023). "In chronic GVHD, mBreg cells can provide protection by the suppressive effects and inhibit proliferation of effector T cells through IL‐10 secretion and cell‐to‐cell contact involving CTLA-4." (PMID 33343576, 2020). "On the other hand, a combination of same genotypic IL-10 production with patient IL-10Rβ A/A genotype protected from chronic GvHD (OR = 0.407, p = 0.0097)." (PMID 19409109, 2009). "Moreover, cord blood is rich in interleukin-10-producing regulatory B cells, which suppresses T-cell immune responses and protect against the development of chronic GVHD." (PMID 37782417, 2023). "In the patients, none of the genotypes of IL-10 or IL-10Rβ showed statistically significant association with chronic GvHD." (PMID 19409109, 2009). "Similarly, when the IL-10Rβ A/A homozygous patients received a graft with a same IL-10 production level, they were protected from chronic GvHD (p = 0.0097, OR = 0.407)." (PMID 19409109, 2009). "In a study that examined immune characteristics in patients with chronic GvHD who received MSC therapy, an increase in IL-10-secreting regulatory B cells was demonstrated." (PMID 31188842, 2019). "Theoretically counteracting cytokines (IL-10 and IFN-γ) and T helper subsets (Th1 and Th2) increased at the same time during acute and chronic GVHD and decreased when GVHD resolved." (PMID 22957070, 2012). "The occurrence of the IL-10-592 CC genotype, in either donors or recipients, had no significant impact on acute and chronic graft-versus-host disease." (PMID 34152493, 2022). "CD19+CD24hiCD27+ memory Breg cells exhibit decreased abundance in patients with chronic graft-versus-host disease (cGVHD) after liver transplantation and produce less IL-10 than those from patients without cGVHD and healthy donors." (PMID 33343576, 2020). "However, when the authors measured the IL-10 production by B-cells from patients with GVHD, they observed that B-cells from patients with chronic GVHD produced less IL-10 than healthy donors and patients without chronic GVHD17." (PMID 26795594, 2016). "Patients with refractory chronic graft versus host disease (cGvHD) present lower frequencies of total B cells and CD5+IL-10+ B. However, after three months of MSC treatment patients showed improvement of their symptoms correlating with increased CD5+IL-10+ B cells." (PMID 27956762, 2016).
cryptococcal infection (13 papers, 2015 to 2024). "This study identified elevated IL-10 levels as an independent risk factor for developing disseminated cryptococcosis in the control groups." (PMID 38115055, 2023). "Elevated IL-10 level was identified as an independent risk factor for disseminated cryptococcosis in both the PC and CM groups." (PMID 38115055, 2023). "Several soluble mediators including IL-4, IL-10, IL-17, and GM-CSF have been implicated in the recruitment, differentiation, and activation of DCs in different models of cryptococcal infection." (PMID 30761136, 2019). "Production of the regulatory cytokine IL-10 can be associated with persistent cryptococcal infections, and blocking IL-10 late during cryptococcal infection leads to increased accumulation and activation of pulmonary DCs." (PMID 29543719, 2018). "CD11c- interstitial macrophages are associated with increased IL-10 production, which is detrimental for the clearance of cryptococcal infection; correspondingly, CD11c- interstitial macrophages were increased in unvaccinated groups compared to vaccinated groups." (PMID 38469300, 2024). "Therefore, the development of persistent or progressive cryptococcal infection appears to correlate with excessive IL-10 production while experimental IL-10 deficiency results in an enhanced inflammatory response." (PMID 30761136, 2019). "In murine lung cryptococcal infection, IL-10 signaling reduced the numbers of moDC and the activation of CD11b+ type-2 DCs in an autocrine manner in persistent infection and the ablation of IL-10 promoted the host immunity by these subsets." (PMID 39340013, 2024). "The multivariate logistic regression analysis showed that elevated plasma cytokine IL-10 levels independently contributed to disseminated cryptococcosis in both PC and CM groups." (PMID 38115055, 2023). "This is very important because the highly detrimental effect of IL-10 in cryptococcal infection models, as shown in NT mice, plays a major role in downregulating cryptococcal clearance." (PMID 28596945, 2017). "In support of these findings, others have shown that enhanced IL-10 expression correlates with disseminated cryptococcosis in patients with AIDS." (PMID 27973396, 2016). "In addition, similar responses were observed with IL‐10 blockade in experimental cryptococcal infection." (PMID 32472727, 2020). "A study in a similar setting showed a wide spectrum of pro‐inflammatory protein profile (IFN‐γ, IL‐1β, TNF‐α) and anti‐inflammatory proteins (IL‐10, granulocyte monocytes/macrophage colony stimulating factor (GM‐CSF)) being upregulated in CSF during cryptococcal infection." (PMID 32472727, 2020). "Early or late interruption of IL-10 signaling after establishment of cryptococcal infection reduced fungal burden and dissemination to the brain and was associated with enhanced Th1/Th17 responses and increased activation and recruitment of CD11b+ DCs and exudate macrophages." (PMID 30761136, 2019). "Th2 cytokines such as IL-4 and IL-10 have been shown to have non-protective response against cryptococcal infection and are associated with poor clinical improvement." (PMID 29133871, 2017). "Given the massive tissue burden of cryptococci observed in HIV-associated cryptococcosis, it is plausible that the immune phenotype observed among nonsurvivors in this study was a direct effect of GXM, possibly mediated by the actions of IL-10." (PMID 26768248, 2016). "Severe cryptococcosis in the FcγRIIb−/− mice was demonstrated by high fungal burdens in the internal organs with histological cryptococcoma-like lesions and high levels of TNF-α and IL-6, but not IL-10." (PMID 28074867, 2017).
diabetic retinopathy (13 papers, 2012 to 2025). "In contrast, elevated serum IL-10 decreases the risk of developing diabetic retinopathy." (PMID 37108092, 2023). "The levels of cytokines, inflammatory cells, and angiogenic factors increase following diabetic retinopathy (DR), and the association between interleukin-10 (IL-10) gene rs1800896 polymorphism (IL-10 -1082G/A polymorphism) and DR in different populations has been extensively studied." (PMID 30890581, 2019). "Decreased IL-10 levels are seen in diabetic retinopathy patients that have been suggested to be due to increased HDAC11 activity in conjunction with miR-19a in peripheral B cells of diabetic retinopathy patients." (PMID 29085333, 2017). "Similarly, a pro-inflammatory phenotype in T1DM patients with diabetic retinopathy was reported, marked by increased production of IL-6, IL-10, and IL-17A by myeloid cells, alongside reduced IFN-γ production by T cells." (PMID 41280935, 2025). "In addition, the protective effect of IL-10 against diabetic retinopathy supports further development of recombinant IL-10 analogs (such as Pegilodecakin) that delay disease progression by regulating inflammation of the retinal microenvironment." (PMID 40687727, 2025).
filariasis (13 papers, 2010 to 2023). "infection when co-infected with filariasis, according to the association with a higher IL-10/TNF-α ratio, and when co-infected with intestinal parasites, according to the association with a higher IL-10/IL-6 ratio." (PMID 35421083, 2022). "Recently, levels of IL-10 have been directly linked to parasite survival, overcome resistance, and allow full patency in murine filariasis." (PMID 25061608, 2014). "IL-4 and IL-10 are the key cytokines of effector mechanism in murine filariasis and filarial infections diminish both Th1 and Th2 pathways for survival, therefore, protective immunity required activation of both the arms of immune response." (PMID 27828973, 2016). "Also, Tregs from filariasis-infected individuals produce IL-29, a member of the IL-10 cytokine family, which exhibits antitumor and antiviral activities that programs naïve DCs to induce Treg differentiation." (PMID 29483912, 2018). "It is generally accepted that during filariasis, IL-10 and TGF-β play an immunosuppressive role but the source of IL-10 remains inconclusive." (PMID 22509424, 2012). "A study evaluating PBMC from patients with filariasis, showed that CD4+ T cells are the main source of IL-10 and the majority of these cells co-produced neither IL-4 nor IFN-γ." (PMID 33692784, 2021).
head and neck squamous cell carcinoma (13 papers, 2011 to 2025). A squamous cell carcinoma that arises from any of the following anatomic sites: lip and oral cavity, nasal cavity, paranasal sinuses, pharynx, larynx, and salivary glands. "Another study showed that recombinant IL-10 can boost the suppressive effect exerted by the supernatants of different head and neck squamous cell carcinoma (HNSCC) cell lines on the IFNα secretion ability of pDCs." (PMID 33919546, 2021). "The increase expression of IL-10 in head and neck squamous cell carcinoma patients remains controversial." (PMID 25153698, 2014). "Knockdown of semaphorin 4d (Sema4D) in a human head and neck squamous cell carcinoma (HNSCC) cell line resulted in a loss of MDSC function, as shown by a decrease in the production of the immunosuppressive cytokines arginase-1, TGF-β, and IL-10 by MDSCs." (PMID 37039643, 2023). "IL-10 and VEGF have been detected in head and neck squamous cell carcinomas, and a higher expression of these cytokines correlates with the tumor grade and progression as well as a reduced patient survival time." (PMID 24213108, 2011). "IL-33 could support the expansion of ST2+Foxp3+ Treg cells, increasing the secretion of inhibitory cytokines IL-10 and TGF-β1 in ST2+Foxp3+ Treg cells and promoting their suppressive function in head and neck squamous cell carcinoma (HNSCC)." (PMID 34177907, 2021). "Additionally, a positive correlation between Treg concentration in the TME and serum IL-10 levels, as well as the extent of CCL22-positive cell infiltration, has been documented in patients with head and neck squamous cell carcinoma (HNSCC) and ESCC." (PMID 40134607, 2025).
hookworm infection (13 papers, 2008 to 2026). "Hookworm infection is associated with higher levels of IL-10 and lower levels of both Th1 and Th2 cytokines." (PMID 33832450, 2021). "Hookworm infections were also associated with increased levels of the anti – inflammatory cytokine – IL-10, which was positively correlated with levels of lipopolysaccharide (LPS)." (PMID 23056659, 2012). "Moreover, hookworm infection and subsequent treatment reshape the immune landscape, highlighting the contribution of Tfh- and Th17-associated pathways, as well as IL-9 and IL-10 production, in modulating host-parasite interactions." (PMID 41823215, 2026). "Together, our results suggest that hookworm infection elicits and expand the activation of regulatory monocytes, with downmodulation of IL-12 at a higher extent than IL-10 expression, which might be associated with modulation of the host’s immune response and prolonged survival of the parasite." (PMID 28390393, 2017). "There were no significant changes in cytokines involved in type 1 immune responses, chemokines, serum antibodies, or the immunoregulatory cytokines, TGF-β1 and IL-10, during the controlled hookworm infection." (PMID 39411786, 2024). "Previous studies have showed that human hookworm infection induces peripheral immune responses characterized by increased frequency of regulatory T cells, high levels of circulating IL-10, induction of T lymphocytes apoptosis and modulation of Th17 responses." (PMID 28390393, 2017). "Both the regulatory cytokines, TGF-β and IL-10, were induced by hookworm infection, but this was only evident in mucosa restimulated with NaES." (PMID 22346753, 2012). "Our results show that experimental hookworm infection leads to a strong systemic and mucosal Th2 (IL-4, IL-5, IL-9 and IL-13) and regulatory (IL-10 and TGF-β) response, with some evidence of a Th1 (IFN-γ and IL-2) response." (PMID 22346753, 2012). "Considerable antigen-induced IL-10 secretion has been described in individuals with hookworm infection." (PMID 21909439, 2011). "Our data also reveal that at least one dominant counter-regulatory mechanism i.e. increased IL-10 production might potentially protect against systemic immune activation in hookworm infections." (PMID 23056659, 2012). "While Th2 responses to hookworm antigens are well described, a study conducted in Brazil found elevated spontaneous cellular secretion of tumor necrosis factor alpha, a pro-inflammatory cytokine, and interleukin (IL)-10 in individuals with patent hookworm infections." (PMID 18523547, 2008). "The enhanced IL-10 production may be a mechanism to regulate pathology due to inflammatory responses elicited by the infection Hookworm infection is very common in Africa, however its effect on malaria vaccine candidate antigens such as GMZ2 have not been extensively investigated." (PMID 33832450, 2021). "Our results showed that hookworm infection induce an augmentation of Tregs in the peripheral blood, followed by the higher levels of circulating Treg cells expressing several markers and cytokines associated with cell regulation (CTLA-4, GITR, IL-10, TGF-β and IL-17)." (PMID 22087344, 2011). "Thus we hypothesise that hookworm-induced TH2 and IL-10 cross-regulation of the TH1/TH17 inflammatory response may be responsible for the suppression of these responses during experimental hookworm infection." (PMID 21949691, 2011). "Therefore hookworm infection may be inducing IL-10, which in turn is suppressing the TH1/TH17 response, however a larger study is required to confirm the existence of a pre-gluten challenge IL-10 response." (PMID 21949691, 2011). "Finally, individuals from the HWI group had a significantly higher frequency of CD206+CD23+IL-10+ (7.57 ± 1.96) cells compared to individuals from the NI group (0.35 ± 0.09) (p < 0.001), suggesting that activated monocytes are a potential source of regulatory cytokines during hookworm infection." (PMID 28390393, 2017).
hookworm infection (continued). "In fact, a prominent rise in IL-10 secretion was demonstrated in ES antigen-stimulated PBMC cultures during primary experimental and natural human hookworm infection." (PMID 22087344, 2011). "Even though there was an unexpected negative correlation between parasite load and IL-10 secretion of lymphocytes, the antigen-induced IL-10 secretion was significantly associated with mono-infected individuals, indicating its importance in immune regulation during hookworm infection." (PMID 21909439, 2011). "Hookworm infection suppressed basal production of the inflammatory cytokines IFN-γ and IL-17A, and our data indicate that this suppression may be dependent upon skewing or cross-regulation of the celiac response by a concurrent TH2 response, and/or IL-10 production." (PMID 21949691, 2011). "Our study also reveals that MT in hookworm infections (unlike HIV) does not directly translate to systemic immune activation, perhaps due to counter-regulatory measures, such as increased IL-10 production, induced by the parasite." (PMID 23056659, 2012).